TNFRSF10D (TNF receptor superfamily member 10d)
Description:
Receptor for the cytotoxic ligand TRAIL. Contains a truncated death domain and hence is not capable of inducing apoptosis but protects against TRAIL-mediated apoptosis. Reports are contradictory with regards to its ability to induce the NF-kappa-B pathway. According to PubMed:9382840, it cannot but according to PubMed:9430226, it can induce the NF-kappa-B pathway.
Synonyms: DcR2; TRAIL-R4; CD264; TRAILR4; TRUNDD
Tractability: Antibody: its Gene Ontology location is reachable by antibodies, with high confidence; UniProt predicts a signal peptide or a membrane-spanning region; the Human Protein Atlas places it where antibodies can reach. PROTAC: ubiquitination databases record sites on it.
Gene: Protein-coding gene on chromosome 8 (23,135,588 to 23,164,027, reverse strand). Ensembl gene ENSG00000173530.
Subcellular location: Membrane
Subcellular location (Human Protein Atlas): Actin filaments; Plasma membrane
Pathways (Reactome):
Hemostasis: Cell surface interactions at the vascular wall
Signal Transduction: TRAIL signaling
Gene Ontology:
Molecular function: protein binding; receptor decoy activity; TRAIL binding
Cellular component: cell surface; plasma membrane; membrane
Genetic constraint (gnomAD): Loss-of-function variants: 25 observed, 38.07 expected, observed/expected ratio (o/e) 0.66, 90% interval 0.48 to 0.92. The upper end of that interval is the gene's LOEUF score, 0.92, which puts it in group 3 of 6, group 1 being the genes least tolerant of losing a copy. Missense variants: 481 observed, 483.6 expected, observed/expected ratio (o/e) 0.99, 90% interval 0.92 to 1.07. Synonymous variants: 181 observed, 191.16 expected, observed/expected ratio (o/e) 0.95, 90% interval 0.84 to 1.07.
Homologues: Orthologues: chimpanzee TNFRSF10D (89% identical), zebrafish nradd (15% identical), zebrafish tnfrsf1b (12% identical), tropical clawed frog nradd (12% identical), zebrafish tnfrsf11a (12% identical), zebrafish tnfrsfa (11% identical), tropical clawed frog tnfrsf10b (10% identical), zebrafish hdr (10% identical), mouse Tnfrsf22 (10% identical), mouse Tnfrsf23 (10% identical), zebrafish cd40 (10% identical), rat Tnfrsf26 (9% identical), and 2 more. Paralogues in human: TNFRSF10B (48% identical), TNFRSF10A (47% identical), TNFRSF10C (33% identical), TNFRSF21 (16% identical), TNFRSF1A (14% identical), LTBR (13% identical), NGFR (13% identical), TNFRSF11A (13% identical), TNFRSF1B (12% identical), TNFRSF25 (12% identical), TNFRSF8 (12% identical), TNFRSF4 (12% identical), and 9 more.
Diseases named in the same sentence as TNFRSF10D in open-access papers:
TNFRSF10D is named in the same sentence as 50 diseases in open-access papers, as found by Europe PMC text mining. Sharing a sentence is not in itself a finding about the gene and the disease. The quoted sentences say what the papers report.
breast carcinoma (6 papers, 2005 to 2021). "Through the TNFRSF10C and TNFRSF10D mRNA expression was inversely correlated with expression levels of miR-193 and miR-210 in breast cell lines and breast cancer patients, respectively." (PMID 33461524, 2021). "The TNFRSF10C and TNFRSF10D mRNA expression inversely correlated with the expression levels of miR-193 and miR210 in breast cell lines and breast cancer patients, respectively." (PMID 33461524, 2021).
melanoma (5 papers, 2009 to 2022). A malignant, usually aggressive tumor composed of atypical, neoplastic melanocytes. "Further studies are needed to elucidate how TNFRSF10D promoter hypermethylation is associated with poor prognosis and aggressive proliferation in melanoma." (PMID 25003639, 2014). "At two of these genes, THBS1 and TNFRSF10D, we identified a positive association between total body nevus count and promoter CpG methylation, in line with their findings of increased DNA methylation in advanced stage melanoma." (PMID 27993549, 2017). "On average, the COL1A2 and TNFRSF10D promoters appeared >10–fold more methylated in melanoma cell lines compared to melanocytes, and 6-fold higher in the fresh tumors." (PMID 22028813, 2011). "In this study, we demonstrate that TNFRSF10D DNA-methylation analysis of a small tissue-punch from archival FFPE melanoma tissue is a promising approach to provide prognostic information in patients with melanoma." (PMID 25003639, 2014). "Our data demonstrate that DNA-methylation analysis of the TNFRSF10D promoter from a small tissue punch from archival paraffin-embedded melanoma tissue is able to provide independent prognostic information in order to identify patients with a higher risk for aggressive progress." (PMID 25003639, 2014). "We confirm previous reports that COL1A2, THBS1, TNFRSF10D and UCHL1 are highly methylated in melanoma, thus providing further evidence that these genes are highly important in melanocytic neoplasia." (PMID 22028813, 2011). "Summary of COL1A2, THBS1, TNFRSF10D and UCHL1 methylation in melanocytes, melanoma cell lines, fresh-frozen melanoma tumors and other cancer cell lines." (PMID 22028813, 2011). "For TNFRSF10D, 31 of 43 (72%) melanoma cell lines had no mRNA expression." (PMID 22028813, 2011).
prostate carcinoma (5 papers, 2011 to 2023). A carcinoma that arises from epithelial cells of the prostate gland. "TNFRSF10D is negatively correlated with the biochemical recurrence risk score of prostate cancer, suggesting that the overexpression of TNFRSF10D can reduce the incidence of biochemical recurrence." (PMID 36142828, 2022). "In this study, we constructed a model using a Cox proportional hazards model based on the expression of eight immune-related genes that were associated with prognosis in prostate cancer: EDNRB, ANGPTL2, TNFSF15, TNFRSF10D, EDN2, BMP2, NLRP14, and PLK1." (PMID 33197890, 2020).
glioma (3 papers, 2011 to 2026). A benign or malignant brain and spinal cord tumor that arises from glial cells (astrocytes, oligodendrocytes, ependymal cells). "While THBS1 was only methylated in the colon cancer cell lines (43% methylation), TNFRSF10D appeared to be the only gene methylated in the glioma lines (33%)." (PMID 22028813, 2011). "Although the prognostic value of TNFSF10C and TNFRSF10D has not been previously investigated in glioma, these proteins have the potential to be used as novel biomarkers." (PMID 36609243, 2023).
glioblastoma (2 papers, 2013 to 2026). The most malignant astrocytic tumor (WHO grade IV). "A tumor necrosis factor receptor or death receptor family members were found frequently methylated in glioblastoma: TNFRSF10D promoter methylated in 100%, and TNFRSF10A in 68% of glioblastomas." (PMID 23320456, 2013).
Myeloma (2 papers, 2015 to 2024). "Myeloma cells with TRAF3 and WHSC1 mutations and overexpression of TNFRSF10D, NCR3LG1, ULBP1, PVR, and PCGF5 were tolerance to NK cells." (PMID 38410372, 2024). "Myeloma cells with NLRC5 mutations and overexpression of selected genes including TNFRSF10D, NCR3LG1, ULBP1, PVR, and PCGF5 were sensitive to NK cells." (PMID 38410372, 2024).
cystadenoma (1 paper, 2025). A benign or borderline cystic epithelial neoplasm arising from the glandular epithelium. "Regarding TRAF2, RIPK1, TNFRSF10D/TRAIL-R4, and NF-ΚB, differential mRNA expression profiles were identified between the cystadenoma and EOC groups, with statistically significant differences observed between primary and metastatic EOC." (PMID 40943317, 2025).
HCMV infection (1 paper, 2021). "In agreement with previous studies, we confirmed that TNFRSF10D total mRNA was significantly upregulated in uninfected ZAP KO cells but also expressed higher in the context of HCMV infection." (PMID 33947766, 2021).
mantle cell lymphoma (1 paper, 2006). Mantle cell lymphoma is a rare form of malignant non-Hodgkin lymphoma affecting B lymphocytes in the lymph nodes in a region called the ``mantle zone''. "Matrix-based comparative genomic hybridisation (matrix-CGH) analysis demonstrated that TNFRSF10D is one of the pathologically relevant genes in mantle cell lymphoma." (PMID 16449999, 2006).
postpartum hemorrhage (1 paper, 2022). Hemorrhage defined as a blood loss in excess of 500 mL after vaginal delivery or more than 1000 mL after a cesarean delivery. "Eight genes were associated with hemostatic pathways (SELL, CAPZB, SLC16A3, PDPN, TNFRSF10B, SH2B2, NFE2, and TNFRSF10D), which provided novel insights for the prevention and management of postpartum hemorrhage." (PMID 35836580, 2022).
squamous cell carcinoma (1 paper, 2021). A carcinoma arising from squamous epithelial cells. "Compared with adenocarcinoma, squamous cell carcinoma showed strong communications with endothelial by the MIF/TNFRSF10D, EGFR/GRN, EGFR/HBEGF, and EPHB2/EFNB2 interactions." (PMID 34185421, 2021).
ZIKV infection (1 paper, 2017). "Two pro-apoptotic factors, TNFRSF10D and BBC3, were also upregulated about 2-fold at both gene and gene ISO levels by ZIKV infection." (PMID 29116029, 2017). "One recent study reported that several apoptotic regulators, including ZMAT3, PMAIP1, TNFRSF10D, BBC3, were upregulated, and cell cycle genes, such as E2F1 and E2F2, were downregulated after ZIKV infection." (PMID 29116029, 2017).
tumor (34 papers, 2005 to 2026). "Therefore, both TNFSF10, consistently upregulated and TNFRSF10D, consistently downregulated in the scaffold network, play a dual role of tumor suppressors and promoters." (PMID 33287223, 2020). "Among these genes, six (HOXA6, STC2, HSD17B8, TFAP2A, CYP1B1, and HOXC8) were reported to be osteogenesis-/chondrogenesis-related genes, and five (ADRA1A, TSPYL5, TES, TNFRSF10D, and MBP) were reported to be tumor-suppressor genes." (PMID 31889115, 2019). "However, tumor cells often evade apoptosis through the overexpression of decoy receptors, such as TNFRSF10C, TNFRSF10D, and OPG, which activate pro-survival pathways like NF-κB and contribute to metastasis and therapy resistance in many cancers, including in EOC." (PMID 40943317, 2025).
cancer (15 papers, 2011 to 2025). A tumor composed of atypical neoplastic, often pleomorphic cells that invade other tissues. "Hypermethylation and silencing of TNFRSF10D have been reported to occur in multiple cancer types and be associated with poor survival and resistance to DNA‐damaging drugs." (PMID 37830163, 2024). "Regarding the key interaction between T cells and cancer cells, increased expression of ligand-receptor pairs MIF_TNFRSF10D, CD55_ADGRE5, CD226_NECTIN2, CCL3L1_CCR1, and CCL3_CCR1 was observed." (PMID 39986271, 2025). "TNFRSF10D promoter hypermethylation has been described as a mechanism of inactivating this gene in several cancer types." (PMID 22028813, 2011). "The colorectal cancer related protein PABPC4 of the SARS-CoV-2 interactome interacts with YWHAQ, YWHAZ & TNFRSF10D that all involve Apoptosis59." (PMID 36463386, 2022). "A total of 8 cancer genes with an OncoScore above the 90th percentile was identified (TNFRSF10B, TNFRSF10C, TNFRSF10A, TNFRSF10D, LZTS1, NKX3-1, BNIP3L and RHOBTB2; OncoScore range: 71.4–86.3)." (PMID 28387367, 2017).
TNFRSF10D also shares sentences with these, for which no sentence is quoted: colon carcinoma (2 papers); hepatocellular carcinoma (2); infection (2); lung carcinoma (2); pancreatic cancer (2); renal fibrosis (2); acute kidney injury (1); adenocarcinoma (1); Ascites (1); bladder cancer (1); cervical carcinoma (1); cholangiocarcinoma (1); colorectal cancer (1); COVID-19 (1); dementia (1); diabetic nephropathy (1); esophageal cancer (1); gonococcal infection (1); head and neck cancer (1); HIV-1 infection (1); interstitial cystitis (1); invasive ductal carcinoma (1); lichen planus (1); liver fibrosis (1); major depressive disorder (1); metastatic melanoma (1); mild cognitive impairment (1); neuroblastoma (1); nevus (1); osteosarcoma (1).
A further 6 diseases each share a sentence with TNFRSF10D in 1 paper.